NAV3 (neuron navigator 3)
Description:
Is involved in microtubule cytoskeleton organization and plays a role in cell migration.
Synonyms: unc53H3; KIAA0938; POMFIL1; STEERIN3; NEDSFB
Tractability: PROTAC: ubiquitination databases record sites on it; its protein half-life has been measured.
Gene: Protein-coding gene on chromosome 12 (77,324,641 to 78,213,010, forward strand). Ensembl gene ENSG00000067798.
Subcellular location: Nucleus outer membrane; Cytoplasm, cytoskeleton
Subcellular location (Human Protein Atlas): Nuclear membrane; Cytosol
Gene Ontology:
Molecular function: microtubule binding; ATP binding; ATP hydrolysis activity
Biological process: microtubule cytoskeleton organization; negative regulation of cell migration; negative regulation of interleukin-2 production; negative regulation of microtubule depolymerization; positive regulation of microtubule polymerization; nervous system development; neurogenesis
Cellular component: microtubule; microtubule end; nuclear outer membrane; cytoskeleton
Genetic constraint (gnomAD): Loss-of-function variants: 70 observed, 200.64 expected, observed/expected ratio (o/e) 0.35, 90% interval 0.29 to 0.43. The upper end of that interval is the gene's LOEUF score, 0.43, which puts it in group 1 of 6, group 1 being the genes least tolerant of losing a copy. Missense variants: 2,485 observed, 2,801 expected, observed/expected ratio (o/e) 0.89, 90% interval 0.86 to 0.92. Synonymous variants: 1,057 observed, 1,024.1 expected, observed/expected ratio (o/e) 1.03, 90% interval 0.98 to 1.09.
Homologues: Orthologues: chimpanzee NAV3 (99% identical), macaque NAV3 (99% identical), rabbit NAV3 (95% identical), pig NAV3 (93% identical), mouse Nav3 (93% identical), rat Nav3 (93% identical), dog NAV3 (88% identical), guinea pig NAV3 (81% identical), tropical clawed frog nav3 (78% identical), zebrafish nav3 (62% identical), Caenorhabditis elegans unc-53 (18% identical). Paralogues in human: NAV2 (56% identical), NAV1 (34% identical).
Diseases named in the same sentence as NAV3 in open-access papers:
NAV3 is named in the same sentence as 71 diseases in open-access papers, as found by Europe PMC text mining. Sharing a sentence is not in itself a finding about the gene and the disease. The quoted sentences say what the papers report.
breast carcinoma (11 papers, 2011 to 2025). "Another study implicated the role of NAV3 in inhibiting breast cancer progression by regulating microtubule dynamics." (PMID 32029709, 2020). "Using multivariate Cox regression, the prognostic effect of NAV3 was shown to be associated with histological grade (P = 0.0083) and breast cancer subtype (PAM50; P = 0.0178)." (PMID 25678558, 2015). "Congruently, analysis of a larger breast cancer dataset confirmed association between low NAV3 and shorter disease-specific survival of patients (Fig7D; 1,471 patients)." (PMID 25678558, 2015). "When investigating whether NAV3 expression would associate with the recently identified 10 subgroups of breast cancer, low NAV3 was associated with groups with the worst outcome: iCluster5 (P = 5.22e-9), iCluster9 (P = 0.0007) and iCluster10 (P = 1.57e-17)." (PMID 25678558, 2015). "NAV3 has been proposed as a candidate tumour suppressor protein in breast cancer, colon cancer and uterine leiomyoma, though a role for endometrial cancer had not been described." (PMID 40633141, 2025). "Another study showed that silencing NAV3 in breast cancer cells increased cell migration and metastasis, which is concordant with our own findings of a possible increase in migratory capacity in endometrial cells upon NAV3 silencing." (PMID 40633141, 2025). "In recent years, several studies have reported that NAV3 expression was distinctly downregulated in several types of tumors, such as glioma, breast cancer, and uterine leiomyoma." (PMID 35812247, 2022). "NAV3 expression is attenuated in metastatic colon cancer, breast cancer and lung cancer and its knockdown promotes invasive behaviors, platinum drug resistance and epithelial mesenchymal transition in vitro and enhances metastasis in vivo." (PMID 34298611, 2021). "NAV3 silencing in breast cancer cells increased tumorigenicity in a xenograft model, supporting our data here for gliomas." (PMID 32727536, 2020). "Accumulating evidence suggests that disruption of NAV3 contributes progression of breast cancer, colorectal cancer, T-cell lymphoma and nervous system tumors including neuroblastoma." (PMID 27009842, 2016). "We propose that NAV3 inhibits breast cancer progression by regulating microtubule dynamics, biasing directionally persistent rather than random migration, and inhibiting locomotion of initiated cells." (PMID 25678558, 2015). "To enable immunohistochemical analysis of NAV3, we generated a monoclonal antibody, established specificity and analyzed human breast cancer specimens." (PMID 25678558, 2015). "To ascertain involvement of NAV3 in invasiveness, we selected a subline of the highly invasive mammary cancer MDA-MB-231 cells, which overexpresses the red fluorescent protein (RFP)." (PMID 25678558, 2015). "Similarly, NAV3 was previously proposed as a suppressor of migration and metastasis in colon and breast cancer." (PMID 39097525, 2025). "Taken together, two animal models (along with a third, gain-of-function model) indicated that lung metastasis of mammary tumor cells might be accelerated when NAV3 is depleted in tumors." (PMID 25678558, 2015). "The third candidate gene, NAV3 (OMIM*611629), functions as a tumor suppressor in breast cancer and is expressed in the vagina, uterus, cervix, and other tissues." (PMID 40868176, 2025). "NAV3 is a microtubule-binding protein whose expression is regulated by TP73 and induced by EGF in breast cancer cells." (PMID 34298611, 2021). "It is intriguing to speculate whether manipulation of NAV3, the only other gene that displayed both properties of differential connectivity and differential expression across tissue grade, would have similar effects in altering the malignant potential of breast cancers." (PMID 21627793, 2011).
colorectal cancer (7 papers, 2012 to 2025). A primary or metastatic malignant neoplasm that affects the colon or rectum. "Previous studies have reported an association of copy number changes in NAV3 with epithelial cell cancer pathogenesis, colorectal cancers and adenomas while suggesting that this effect may be mediated through inflammatory pathways." (PMID 40633141, 2025). "For example, SRRM4 and NAV3 are reported to regulate lung cancer and colorectal cancer, respectively." (PMID 37604131, 2023). "Abrogation of NAV3 and p73 expression significantly increased the invasion and migration rate of colorectal cancer cells as confirmed by wound-healing, cell invasion, and cell migration assays." (PMID 32029709, 2020). "The current paper describes copy number changes in chromosome 12 centromere, and in the NAV3 gene, located in 12q21, in a substantial number of cases of colorectal carcinomas or colon adenomas." (PMID 22173670, 2012). "Copy number changes in the NAV3 gene have been observed in colorectal cancer." (PMID 33362854, 2020). "Moreover, NAV3 is reportedly involved in the p73-mediated tumor suppression, as well as in Jak-STAT and GnRH signaling in colorectal cancer cells." (PMID 33362854, 2020).
colon carcinoma (6 papers, 2012 to 2025). "Array-CGH analysis of colon carcinoma cell lines showing NAV3 loss by FISH revealed major alterations in chromosome 12, as well as in other chromosomes, as was expected for cultured cancer cells." (PMID 22173670, 2012). "Studies on other genes belonging to the same family (NAV2 and NAV3) showed their opposed roles in colon cancer development." (PMID 35867729, 2022). "NAV3 is upregulated in response to DNA damage in colon carcinoma cells and is involved in the suppression of migration and invasion in vitro." (PMID 34298611, 2021). "These experiments showed that NAV3 knockdown increased colon cancer cell migration and invasiveness in a p73-dependent manner." (PMID 32029709, 2020). "Based on our results on p73kd and NAV3kd cell lines and IHC, we envisage that this significant downregulation of p73 and NAV3 protein levels could promote metastasis in colon cancer." (PMID 32029709, 2020). "Also, IL23R mRNA level was upregulated in a colon carcinoma cell line showing up to 90% cells with NAV3 deletion." (PMID 22173670, 2012). "Immunohistochemistry analysis revealed the downregulation of both NAV3 and p73 expression in metastatic colon cancer tissues as compared to non-metastatic cancer tissues." (PMID 32029709, 2020). "Additionally, the expression pattern of NAV3 and p73 showed extensively significant correlation in both non-metastatic and metastatic human colon cancer tissue samples." (PMID 32029709, 2020). "Furthermore, Immunohistochemistry (IHC) analysis of non-metastatic and metastatic human colon cancer tissue samples revealed that NAV3 and p73 levels were significantly downregulated in metastatic tumor tissue samples as compared to non-metastatic tumor tissue samples." (PMID 32029709, 2020).
Alzheimer disease (5 papers, 2012 to 2024). A progressive, neurodegenerative disease characterized by loss of function and death of nerve cells in several areas of the brain leading to loss of cognitive function such as memory and language. "Downregulation of miR-29a is associated with increased level of NAV3 in Alzheimer disease brains." (PMID 38705955, 2024). "KEGG assays revealed that NAV3 may be involved in Alzheimer disease, amyotrophic lateral sclerosis, Huntington disease, FoxO signaling pathway, and human papillomavirus infection." (PMID 35812247, 2022). "In addition, increased expression of NAV3 mRNA was observed in brain tissue of Alzheimer’s disease and was suggested to be regulated by miR-29a." (PMID 23264780, 2012). "In addition, reduced expression of miR-29 family causes several neurodegenerative disorders, including Alzheimer’s disease, Huntington’s disease, and spinocerebellar ataxias, by targeting voltage-dependent anion channel 1 (VDAC1), β-secretase 1 (BACE1) and neuron navigator 3 (NAV3)." (PMID 29495532, 2018). "Since NAV3 has is part of neural navigator gene family like NAV1 and NAV 2, dysregulation in NAV 3 expression can lead to abnormal neural growth and play a role is disease such as autism spectrum disorders or Alzheimer disease." (PMID 38705955, 2024).
ovarian carcinoma (5 papers, 2016 to 2025). A malignant neoplasm originating from the surface ovarian epithelium. "Studies have found that miR-21-3p can target the regulation of NAV3 gene to reduce the sensitivity of ovarian cancer cells to paclitaxel." (PMID 32943985, 2020). "Among them, there were genes important for signaling (Pik3c3), genes playing a role in breast (Nav3) and ovarian cancers (Epcam)." (PMID 31084621, 2019). "RNA-seq analysis of the 284 ovarian cancer samples available in “The Cancer Genome Atlas” (TCGA) data portal showed a significant correlation between miR-21-3p overexpression, NAV3 downregulation, and cisplatin resistance." (PMID 27166999, 2016).
glioma (4 papers, 2020 to 2025). A benign or malignant brain and spinal cord tumor that arises from glial cells (astrocytes, oligodendrocytes, ependymal cells). "Silencing of NAV3 in vitro also leads to upregulation of IL-23R in colorectal and glioma cell lines, linked to proinflammatory JAK-STAT signaling." (PMID 34298611, 2021). "Functional validation with CRISPR-Cas9-induced mutations in novel genes Tead2, Spred1, and Nav3 demonstrates heightened EGFRvIII-glioma cell proliferation." (PMID 32727536, 2020). "Specifically, NAV3 expression is significantly lower in high‐grade gliomas (grade 4 astrocytoma and glioblastoma) compared to lower‐grade tumors (oligodendroglioma and grade 2 or 3 astrocytoma)." (PMID 39097525, 2025). "Using glioblastoma cell lines and patient‐derived glioma stem‐like cell cultures, we disclose an upregulation of NAV3 in invading glioblastoma cells, contrasting with its lower expression in cells residing in tumor spheroid cores." (PMID 39097525, 2025). "For NAV3 OE studies in glioma cell lines, we utilized a doxycycline‐inducible system to allow for direct comparison of cells with or without induced overexpression of NAV3." (PMID 39097525, 2025). "Collectively, our results imply that the decrease of NAV3 expression levels in GBM likely stems from a large tumor core containing necrotic regions, exhibiting low NAV3, rather than being indicative of a tumor suppressor role of NAV3 in glioma cells." (PMID 39097525, 2025). "GBM exhibit decreased NAV3 expression compared to low‐grade gliomas, and this has led to the perception of NAV3 as a negative regulator of GBM progression." (PMID 39097525, 2025).
melanoma (4 papers, 2015 to 2025). A malignant, usually aggressive tumor composed of atypical, neoplastic melanocytes. "Loss of NAV3 expression has been associated with melanoma and poor survival in breast and nervous system tumors." (PMID 40868176, 2025). "While seldom mutated in cancer, the range of tumors in which aberrant NAV3 expression was encountered is extensive: colorectal, breast, melanoma, adrenal carcinoma, glioblastoma and neuroblastoma." (PMID 32029709, 2020). "Intriguingly, this highlighted NAV3 as being upregulated in mesenchymally invading cells and downregulated in cells employing amoeboid invasion strategies in fibrosarcoma and melanoma cells, in line with results on GBM cells." (PMID 39097525, 2025). "Next, we investigated changes in NAV3 expression levels during cancer invasion plasticity by analyzing our previously acquired transcriptomic data from fibrosarcoma and melanoma cells undergoing MAT and amoeboid‐mesenchymal transition (AMT) in 3D collagen." (PMID 39097525, 2025). "Furthermore, the correlation between cell invasion phenotype and NAV3 expression levels was also established using a set of three melanoma cell lines: mesenchymal BLM, mixed WM3629, and amoeboid A375m2." (PMID 39097525, 2025).
neuroblastoma (4 papers, 2013 to 2019). Neuroblastoma (NB) is the most common solid, extracranial childhood tumor. "Of note NAV3 deletions have been associated with poor prognosis in nervous system tumors including neuroblastoma." (PMID 27009842, 2016). "Other genes (PTK2, NAV3, NAV1, FZD1 and ATRX), expressed in neuroblastoma and involved in cell invasion and migration were mutated at frequency ranged from 4% to 2%." (PMID 27009842, 2016). "In neuroblastomas, the expression of NAV3 decreased but were up-regulated in nerve cells after brain injury, indicating that NAV3 is involved in neuron growth and regeneration as well as neural tumorigenesis." (PMID 24321625, 2013).
autism spectrum disorder (3 papers, 2024 to 2025). A spectrum of developmental disorders that includes autism, and Asperger syndrome. "However, in an exome-wide association study (ExWAS) of a large cohort of patients with autism spectrum disorder (ASD), six genes including NAV3 were significantly associated with ASD as a moderate-risk gene." (PMID 39708122, 2025).
glioblastoma (3 papers, 2015 to 2025). The most malignant astrocytic tumor (WHO grade IV). "Neuron navigator 3 (NAV3), a microtubule‐associated protein affecting microtubule growth and dynamics, is downregulated in various cancers, including glioblastoma, and has thus been considered a tumor suppressor." (PMID 39097525, 2025). "Furthermore, we establish an association between low and high NAV3 expression and the amoeboid and mesenchymal invasive phenotype, respectively, and demonstrate that overexpression of NAV3 directly stimulates glioblastoma invasive behavior in both 2D and 3D environments." (PMID 39097525, 2025). "Overall, our results shed light on the role of NAV3 in glioblastoma invasion, providing insights into this lethal aspect of glioblastoma behavior." (PMID 39097525, 2025).
Intellectual disability (3 papers, 2022 to 2025). "Earlier this year, biallelic and mono-allelic variants in also the NAV3 gene were reported in NDD patients with intellectual disability (ID), microcephaly, and developmental delay." (PMID 39708122, 2025). "For both ITSN1 and NAV3, we identified four partial or whole gene deletions in 33,083 parents without ASD diagnoses or intellectual disability that also show transmission disequilibrium to affected offspring." (PMID 35982159, 2022).
Uterine leiomyoma (3 papers, 2022 to 2025). The presence of a leiomyoma of the uterus. "In uterine leiomyomas, NAV3 expression is significantly reduced, which may be associated with the abnormal activation of the GnRH receptor signaling pathway." (PMID 41091826, 2025). "Studies have shown that the activation of the GnRH receptor signaling pathway is closely related to the growth of uterine leiomyomas, and changes in NAV3 expression may regulate this pathway through a feedback mechanism, thereby affecting tumor progression." (PMID 41091826, 2025).
autism (2 papers, 2022 to 2024). Persistent deficits in social interaction and communication and interaction as well as a markedly restricted repertoire of activity and interest as well as repetitive patterns of behavior. "In conclusion, taken together with prior studies, biallelic and mono-allelic variants of NAV3 are responsible for a spectrum of NDDs with clinical features including ID, microcephaly, global developmental delay, or autism." (PMID 38977784, 2024). "The association of NAV3 with autism risk is primarily driven by rare inherited loss-of-function (LoF) variants, with an estimated relative risk of 4, consistent with moderate effect." (PMID 35982159, 2022). "NAV3’s association to autism is primarily driven by rare inherited variants." (PMID 35982159, 2022).
cognitive disorder (2 papers, 2022 to 2023). A disease affects cognitive processes. "Autistic individuals with LoF variants in the four moderate-risk genes (NAV3, ITSN1, SCAF1 and HNRNPUL2; n = 95) have less cognitive impairment than 129 autistic individuals with LoF variants in highly penetrant genes (CHD8, SCN2A, ADNP, FOXP1 and SHANK3) (59% vs 88%, P = 1.9 × 10−6)." (PMID 35982159, 2022).
cutaneous T-cell lymphoma (2 papers, 2015 to 2019). "Moreover, previous studies identified NAV3 as a putative tumor suppressor in cutaneous T-cell lymphoma and in the associated lung tumors." (PMID 25678558, 2015).
developmental delay (2 papers, 2024 to 2025). "We report five individuals from three unrelated families with biallelic variants in NAV3 with variable dysmorphic features, developmental delay, mild to moderate ID, and behavioral abnormalities." (PMID 39708122, 2025). "Here, we report loss of function variants in NAV3 in patients consistent with dysmorphism, ID, developmental delay, and behavioral abnormalities from three independent families from South Asia and confirm that biallelic variants in NAV3 are associated with recessive NDD." (PMID 39708122, 2025).